RRM2 (ribonucleotide reductase regulatory subunit M2)
Diseases named in the same sentence as RRM2 in open-access papers (continued):
Sharing a sentence is not in itself a finding about the gene and the disease.
cancer (continued). "In contrast, although ATRi reduces RRM1 and RRM2 protein in cancer cells, it does not reduce dCK protein in cancer cell lines." (PMID 36130512, 2022). "Furthermore, the immunohistochemical staining results based on the HPA database revealed a significantly high positivity of the ZWINT, RRM2, NDC80, KIF4A, CEP55, CENPU, and CENPF genes in cancer tissues compared to adjacent normal tissues." (PMID 35028418, 2022). "Similarly, the positive correlation between RRM2 expression and MSI achieved significance (p < 0.05) in five types of cancer, including COAD, LIHC, TGCT, UCS and UCEC, but RRM2 was negatively related to MSI only in STAD and DLBC." (PMID 35740608, 2022). "According to a pan-cancer analysis, RRM2ishighlyexpressed in many cancers, Further experiment has found that RRM2 is significantly upregulated in CRC.RRM2 might serve as a novel potential target for CRC therapy." (PMID 35216602, 2022). "We observed that a substantial number of immune-related pathways had either positive or negative correlations with RRM2 depending on the cancer type." (PMID 36202136, 2022). "Almost all the FRGs in signaling pathways of pan-cancer, STMN1, RRM2, HELLS, FANCD2, and AURKA could significantly activate the cell cycle, but inhibit EMT, DNA damage response, hormones ER, RAS/MAPK, and RTK." (PMID 36349201, 2022). "However, some signaling proteins were found to be common regulatory molecules among the three cancers whereas terminal enzymes, such as EZH2, ENO2, RRM2, and TYMS, were found to be commonly regulated in all the cancers by three different regulatory mechanisms." (PMID 34790674, 2021). "A sufficient supply of deoxyribonucleotides is required for uncontrolled DNA replication in cancer; it is therefore not surprising that RRM2 is often a target of molecular therapy." (PMID 34204789, 2021). "The downregulation of let-7a-5p may be related to barrier abnormalities by targeting ribonucleotide reductase regulatory subunit M2 (RRM2) and C-C motif chemokine receptor 7 (CCR7), which are mainly involved in cancer cell proliferation." (PMID 32806619, 2020). "Ribonucleotide reductase regulatory subunit M2 (RRM2), an enzyme involved in dNTP production, increased dNTP pools and related with purine and pyrimidine metabolism is tumorigenic and upregulated in cancer cells, was also found to be upregulated." (PMID 32509585, 2020). "In addition, the mRNA level of RRM2 was increased during the cancer progression from stage I to III, suggesting that RRM2 plays a role in the tumorigenesis of HCC." (PMID 31936661, 2020). "Notably, the expression of RRM2 and RRM2B were much weaker or even reversely correlated in some types of cancers." (PMID 31637211, 2019). "It has recently been reported that the ATR/Chk1 pathway plays a key role in promoting RRM2 accumulation by stabilizing E2F1 in the S-phase cells, which may be important for countering the replication stress in cancer cells." (PMID 31324785, 2019). "As the acquisition of a migratory and invasive phenotype is necessary for cancer cell dissemination, we examined whether RRM2-c2orf48 regulates NPC cell migration and invasion." (PMID 28906488, 2017). "In patients receiving cisplatin-containing treatment, those whose cancer tissues presented a positive RRM2 expression seemed to have worse prognosis than those with a negative RRM2 expression." (PMID 24637958, 2014). "While gene amplification, transcriptional activation, and allosteric activation of RRM2 are some of the known mechanisms for RR induction in chemoresistant cancers, the possibility for miRNA regulation of RRM2 expression has never been investigated." (PMID 23335963, 2013). "RRM2 was selected because this molecule has been shown to be involved in cell proliferation and associated with VEGF production in cancer cells, but never studied in endothelial cells." (PMID 23056178, 2012).
cancer (continued). "The IHC staining results from the Human Protein Atlas (HPA) suggested that there was the highest percentage of high/medium staining of RRM2 in iCCAs among 21 different types of cancers, while no RRM2 staining was detected in normal bile duct cells or hepatocytes." (PMID 39243109, 2024). "RRM2 was reported to increase malignancy features of several cancers, but not yet in iCCA." (PMID 39243109, 2024). "However, RRM2 in HCC, one of the most common cancers, remained to be further elucidated." (PMID 37056349, 2023). "In addition, the correlation coefficients landscape calculated by XCELL algorithms showed that RRM2 expression had a negative and significant association with the NKT cells infiltration in the majority of cancers." (PMID 35740608, 2022). "Our data revealed that RRM2 expression was significantly up-regulated compared to corresponding noncancerous tissues in a variety of cancers, regardless of gene or protein expression levels, indicating the extensive oncogenic properties of RRM2 in cancers and promising prospects for cancer research." (PMID 36518297, 2022). "However, CCNF-associated mechanisms are not fully clarified in BRCA, although its binding partner RRM2 (an oncogenic factor) was found to be overexpressed in numerous cancers, including BRCA." (PMID 34201347, 2021). "mTOR signaling may promote the survival of cancer cells via enhancing the expression of FANCD2, CHK1 and RRM2 through CDK4/6 while inhibiting ATM, revealing the potential mechanisms of the increased cancer cell growth and proliferation under stressful conditions." (PMID 31285446, 2019). "Importantly, a second RRM domain (RRM2) of RBM10 recognizes a C-rich sequence, which explains its known interaction with the intronic 3 ́ site of NUMB exon 9 contributing to regulation of the Notch pathway in cancer." (PMID 28379442, 2017). "Importantly, none of these cells (non-malignant or non-GBM cancers) exhibited either reduced RRM2 protein levels or S-phase arrest, thereby indicating a unique mechanism used by GBM cells for protection to supra-physiological levels of RS." (PMID 27845331, 2016). "CKS2 (chr9q22.2), CEP55(chr10q23.33), UHRF1 (chr19p13.3), RRM2 (chr2p25.1), AURKA (chr20q13.2), FLJ39632 (chr14q11.2), FAM83D (chr20q11.23), NEK2 (chr1q32.3) and MAD2L (chr4q27) were all located on PCSRs and showed over-expression in the 9, 8, 10, 9, 8, 9, 9, 8 and 9 types of cancers, respectively." (PMID 24796549, 2014). "However, in 3 patients who had cancer tissues negative for RRM2, none of them showed recurrence or expired." (PMID 24637958, 2014). "Focusing on let-7c-5p, a miRNA of particular interest due to its significant negative correlation with RRM2, we compared its expression levels between 512 LUAD cancer samples and 20 standard samples using box plots." (PMID 41357570, 2025). "We discovered that RRM2 expression did not significantly change in BRCA, CCRCC, or OV compared to normal tissues; however, it significantly increased in the remaining 13 cancer types." (PMID 40732324, 2025). "The results showed that apart from EPAS1 and RAD51AP1 that without immunohistochemistry data, SQLE, CAPG, RRM2, SLC1A5, and SRC as dangerous genes were higher expressed in cancer tissues." (PMID 37461802, 2023). "The results found that mRNA expression of RRM2, but not FST, was significantly higher in cancer tissues than that in normal tissues." (PMID 31936661, 2020). "Using the same approach, we have confirmed BRCA1 binding to RRM2 promoter in NHA-DRB and BJ cells, but not in non-GBM cancer cell lines PC3, HELA; OVCAR5 or Cal51." (PMID 27845331, 2016).
cancer (continued). "However, the impact of RRM2 on the sensitivity of PCA to docetaxel treatment is not yet clear.Annexin A1 (ANXA1) is a calcium dependent phospholipid binding protein closely related to various cellular activities, such as inflammation and apoptosis, as well as cancer cell proliferation." (PMID 37968699, 2023).
infection (12 papers, 2010 to 2025). The state of being infected such as from the introduction of a foreign agent such as serum, vaccine, antigenic substance or organism. "RRM2 is the regulatory component of RR; therefore, research has predominantly focused on investigating RRM2 during infection with DNA viruses and retroviruses." (PMID 41341853, 2025). "Western blot analysis indicated that infection with DENV-1 or DENV-2 increased the expression level of RRM2 protein compared to that in mock-infected cells." (PMID 41341853, 2025). "HuH-7 cells were transfected with the mTOR expression plasmid, either alone or co-transfected with RRM2 or control siRNA, followed by infection with DENV-2 at an MOI of 0.1." (PMID 41341853, 2025). "In future studies, it would be important to validate the effect of RRM2 on furin expression and prM cleavage during infection with other flaviviruses." (PMID 41341853, 2025). "HuH-7 cells were transfected with the RRM2 expression plasmid (pcDNA6/myc-His-RRM2) or the empty vector control pcDNA6/myc-His 24 h prior to either mock infection or infection with DENV-2 (MOI = 0.1)." (PMID 41341853, 2025). "RRM2 modulates the intracellular dNTP pools indispensable for viral DNA synthesis during infection of hepatitis B virus, human papillomaviruses, and Kaposi sarcoma-associated herpes virus." (PMID 41341853, 2025). "Cells were harvested 48 h after infection, and cell lysates were immunoprecipitated using an anti-RRM2 antibody." (PMID 41341853, 2025). "The expression of RRM1 decreased at both 6 h and 72 h of PHH after infection with HCV, while the expression of RRM2 decreased at 6 hrs but increased at 72 h of PHH after infection with HCV." (PMID 37513740, 2023). "CD177 and RRM2 were also upregulated at the initial phase of active infection (0 weeks) compared with that at 8 weeks of follow-up." (PMID 37434783, 2023). "Parallel to upregulation of core histones, the CD177 gene (a neutrophil-specific marker), MYBL2 and RRM2 were highly expressed during the active phase of infection (0 weeks) and the expressed genes were reduced at 8 weeks after therapy." (PMID 37434783, 2023). "We started with the analysis of the expression pattern of TS, RRM1 and RRM2 (two subunits of RR) in SK-Mel-19 and SK-Mel-29 cells 6 days post-infection with control or MYC shRNAs, i.e. at the time point when the majority of MYC-depleted cells underwent senescence." (PMID 23249808, 2012). "Genes involved in pyrimidine metabolism (RRM2, CTPS1, TK1, NME1, NME2, and UCK2) were induced after infection with swH1N1 compared to huH1N1." (PMID 39247193, 2024). "RRM2 and insulin-like growth factor-2 messenger ribonucleic acid (mRNA)-binding protein 3 (IGF2BP3) gene knockdown was achieved by infection with lentiviruses." (PMID 38820515, 2024). "In agreement with the RNA-seq results, RRM2, CTPS1, and TK1 were significantly expressed after infection with swH1N1 relative to the pigs infected with huH1N1." (PMID 39247193, 2024). "We noted a high level expression of RRM2, MYBL2, and some other genes such as GALNT14, CENPU, ACOXL, and U2 at 0 weeks during active phase of infection, which were downregulated at 8 weeks after therapy." (PMID 37434783, 2023). "In contrast with that of mock-infection, the expression of RRM1 and RRM2 decreased 6 h after Huh-7.5 cells were infected with HCV." (PMID 37513740, 2023). "In contrast with that of mock-infection, the expression of RRM1 and RRM2 decreased 6 h after PHH cells were infected with HCV." (PMID 37513740, 2023). "RRM2 has been shown to be required for HCV RNA replication, as siRNA-mediated silencing of RRM2 suppressed HCV replication and infection, while RRM2 overexpression rescued the same." (PMID 36768940, 2023). "HuH-7, HepG2, and A549 cells were reverse-transfected with RRM2 siRNA or non-targeting control siRNA one day before infection with DENV-1 and DENV-2 at a multiplicity of infection (MOI) of 0.1." (PMID 41341853, 2025).
infection (continued). "HuH-7 cells were reverse-transfected with RRM2 or non-targeting control siRNA before infection with DENV-1 or DENV-2 (MOI = 0.1)." (PMID 41341853, 2025). "RRM2, CTPS1, and TK1 were highly expressed after infection with swH1N1 compared to huH1N1." (PMID 39247193, 2024). "In the healed group (n = 17), RRM2 and MYBL2 were significantly upregulated during active infection at 0 weeks but became downregulated at 8 weeks following therapy (p = 3.61E-07 and 2.7E-06 with corresponding FDR values of 0.001994 and 0.006835, respectively)." (PMID 37434783, 2023). "Of the top 10 transcripts upregulated at peak HIV-1 viral load, the majority (6 out of 10) were related to cell cycle and cell division including RRM2, MYBL2, CDK1, UBE2C, CDC45, and TK1 with 8 to 15-fold increased expression compared to the pre-infection samples." (PMID 31937782, 2020). "The presence of background infection in HU-treated cells with high titer virus challenge, despite using higher inhibitor concentrations, could be attributed to the more pronounced inhibition of RRM2, but not RRM2B, by HU." (PMID 40586616, 2025).
adenocarcinoma (5 papers, 2015 to 2023). A common cancer characterized by the presence of malignant glandular cells. "The expression levels of RRAGB, RSPH9, RPS6KL1, RXFP1, and RTL1 mRNA were significantly lower and the RRM2 mRNA level was significantly higher in the high-risk group than those in the low-risk group in NSCLC adenocarcinoma of GSE11969." (PMID 31886214, 2019). "However, quantitative differences in the expression of Tk1, Top2a, Hmgb2, Rrm2, Kpna2, and H1fx were observed and were found to be strongly up-regulated in small-sized adenocarcinomas." (PMID 27602772, 2016). "This signature and the genes RRAGB, RSPH9, RPS6KL1, RXFP1, RRM2, and RTL1 included in this model are independent biomarkers for prediction of overall survival of NSCLC adenocarcinoma." (PMID 31886214, 2019). "Our six-gene prognostic signature for NSCLC adenocarcinoma include RRAGB, RSPH9, RPS6KL1, RXFP1, RRM2, and RTL1 genes which are not contained in the previous gene signatures." (PMID 31886214, 2019).
heart diseases (1 paper, 2022). "Our data showed that in vitro and in vivo, DOX-induced cardiotoxicity was significantly reduced when RRM2 was overexpressed, which indicated that RRM2 exerts a protective effect in heart diseases." (PMID 35204799, 2022). "This study aimed to analyze the unique function of RRM2 in heart diseases." (PMID 35204799, 2022).
hematological malignances (1 paper, 2019). "There are other efficient RRM2 inhibitors such as hydroxyurea (HU), already used in the treatment of hematological malignances, and Triapine (3AP), evaluated in a number of clinical trials and showed encouraging results in anticancer treatment." (PMID 31119182, 2019).
kidney diseases (1 paper, 2021). "Therefore, it is urgent to further explore the roles of RRM2 in renal allograft and other non-cancerous kidney diseases." (PMID 34338139, 2021).
neurodegenerative disease (1 paper, 2022). A disorder of the central nervous system characterized by gradual and progressive loss of neural tissue and neurologic function. "RRM2 is responsible for catalyzing synthesis of deoxyribonucleotides for the purpose of DNA synthesis for cell proliferation, and with relevance to neurodegenerative diseases, RRM2 is required for DNA damage repair through delivering deoxyribonucleotides to the sites of DNA damage." (PMID 35895140, 2022).
vasculopathy (1 paper, 2020). "Thus, our identified DEGs (RRM2, APC, CHEK1, E2F6, TYMS, E2F7, and CDK6) from the cluster 2 subnetwork are highly related to and consistent with the members of the signaling pathways associated with the immune system, apoptosis, the cell cycle, and vasculopathy." (PMID 32426333, 2020).
RRM2 also shares sentences with these, for which no sentence is quoted: oral squamous cell carcinoma (8 papers); head and neck squamous cell carcinoma (6); cholangiocarcinoma (4); endometrial carcinoma (4); stomach cancer (4); kidney cancer (3); lung squamous cell carcinoma (3); acute myocardial infarction (2); adenoma (2); atypical teratoid rhabdoid tumor (2); autoimmune disease (2); Clear cell renal cell carcinoma (2); colon adenocarcinoma (2); ductal breast carcinoma in situ (2); esophageal squamous cell carcinoma (2); gastric adenocarcinoma (2); mesothelioma (2); prostate adenocarcinoma (2); uveal melanoma (2); adrenal tumors (1); age (1); age-related macular degeneration (1); anemia (1); Azoospermia (1); benign tumors (1); bladder tumor (1); bladder urothelial carcinoma (1); brain tumor (1); breast tumor (1); Burkitt lymphoma (1).
A further 48 diseases each share a sentence with RRM2 in 1 paper.